UHRF1 (ubiquitin like with PHD and ring finger domains 1)
Diseases named in the same sentence as UHRF1 in open-access papers (continued):
Sharing a sentence is not in itself a finding about the gene and the disease.
cancer (continued). "Importantly, UHRF1 is regarded as a potential target in anticancer therapy since its expression is upregulated in multiple tumors, and its downregulation was reported to lead to growth arrest and apoptosis of cancer cells." (PMID 34681943, 2021). "Indeed, enhanced UHRF1 expression was identified in all cancers so far examined." (PMID 31249594, 2019). "Furthermore, we surmised whether downregulation of UHRF1/DNMT1 by 2i could be explored for targeting aberrant DNA methylation in cancer cells." (PMID 30696879, 2019). "Thus, the regulation of DNA methylation homeostasis in cancers is likely complicated and influenced not only by the elevated expression of UHRF1/DNMT1 but also by other parameters such as the activity of UHRF1/DNMT1, expression and activity of de novo DNA methyltransferases and TET family proteins." (PMID 30696879, 2019). "Therefore, caution should be maintained while targeting UHRF1 for cancer treatment." (PMID 31245293, 2019). "Therefore, small molecule therapeutics, targeting UHRF1 and/or the SRA domain, could emerge as a low-risk anti-cancer therapy." (PMID 29899856, 2018). "We next examined whether the suppression of UHRF1 could down-regulate the stemness of cancer cells." (PMID 30174788, 2018). "Therefore, the development of reliable, sensitive and non-invasive methods to detect UHRF1 may facilitate cancer diagnosis and disease prognosis." (PMID 29899856, 2018). "Therefore, in a subset of cancers, small molecule UHRF1 inhibitors may restore normal gene expression and serve as useful anti-cancer therapeutics." (PMID 29899856, 2018). "We analyzed the expression levels of UHRF1 in the PANCAN dataset and found that high UHRF1 expression levels (p < 0.0001, n = 5150) strongly predicted poor survival rates compared to low levels (n = 5189), illustrating the importance of these methylation genes in human cancers." (PMID 30190481, 2018). "The different effects of UHRF1 on E-cadherin expression may due to different cancer cell types." (PMID 29080116, 2018). "We postulated that the overexpression of UHRF1 observed in cancer cells could be a result of an alteration of the degradation pathways, pointing out the interest of investigating the degradation pathways of UHRF1, which is one of the goals of the present study." (PMID 29983883, 2018). "Therefore, following UHRF1 levels in fluids or tissues during cancer treatment could be of help in a theranostic context." (PMID 28881702, 2017). "However, the precise role of UHRF1 in cancer remains controversial." (PMID 28584306, 2017). "However, the precise mechanism by which UHRF1 deficiency contributes to cancer progression has not yet been elucidated." (PMID 28584306, 2017). "Thus, one might expect that UHRF1-staining should be lower than Ki67 in normal tissues and as much as Ki67 or above in cancer cells." (PMID 28881702, 2017). "Besides increased expression of UHRF1, increased stability of UHRF1 mRNA through down-regulation of regulatory micro RNAs and increased stability of UHRF1 protein also contribute to abnormal high levels of UHRF1 in different cancers." (PMID 28881702, 2017). "By negatively modulating UHRF1 expression, we further showed that UHRF1 deficiency in itself is sufficient to increase the migratory and invasive properties of cells via inducing EMT, increasing the tumorigenic capacity of cells and leading to the expansion of cancer stem-like cells." (PMID 28584306, 2017). "By its original structure, UHRF1 might be the driver of this complex to ensure the replication of the epigenetic code (DNA methylation and histone code) after DNA replication, allowing cancer cells to conserve the silencing of TSGs during cell division." (PMID 27839516, 2016).
cancer (continued). "The widespread UHRF1/2 overexpression in cancers shown in this and previous studies provides an alternative and possibly more prevalent mechanism for inactivating or suppressing DNMT3A activity in cancers, which may in turn promote tumorigenesis through consequent DNA hypomethylation." (PMID 27462454, 2016). "Thus, the destabilization and mis-targeting reported in their study may operate under excessive UHRF1 overexpression, as they suggested, whereas the negative regulation of DNMT3A by UHRF1/2 reported in our study occurs in both regular and cancer cells." (PMID 27462454, 2016). "Since UHRF1 over‐expression occurs in other cancers, its ability to regulate the Keap1–Nrf2 pathway may be critically important to the malignant behaviour of these cancers." (PMID 26497117, 2016). "Thus, UHRF1/2 represents a novel drug target for cancer therapy." (PMID 27462454, 2016). "Expression of UHRF1 might be used as a progression marker in cancer." (PMID 27072587, 2016). "Summarizing the inferred partial correlation (or direct influence) networks for each cancer type across all cancers predicts that overexpression of UHRF1 and WHSC1 and underexpression of CBX7 could be key drivers of cancer DNA hypermethylation and DNA hypomethylation, respectively." (PMID 26169266, 2015). "Thus, our study predicts that UHRF1 may be an important driver of the aberrant DNA hypermethylation seen in cancer." (PMID 26169266, 2015). "Thus, our data revealed that the global DNA hypomethylation induced by the DNMT1/PCNA/UHRF1 disruption is an oncogenic event of human tumorigenesis, an inducer of epigenetic and genetic signatures frequently observed in several human cancers, and is an initiator of oncogenic events." (PMID 24637615, 2014). "Having established that the depletion of UHRF1 and/or DNMT1 triggers senescence in cancer cells in vitro, we next sought to test if this also occurred in an in vivo setting." (PMID 40595593, 2025). "This enables UHRF1 to bind to MHC‐I, promoting its ubiquitination and degradation, thereby suppressing the antigen presentation pathway and contributing to cancer immunotherapy resistance." (PMID 40673641, 2025). "Ubiquitin-like PHD and RING finger domain 1 (UHRF1) is a major regulator of DNA methylation and is overexpressed in HCC and other cancers." (PMID 41514551, 2025). "UHRF1 (Ubiquitin-like with PHD and RING Finger Domains 1) plays a vital role in maintaining DNA methylation patterns in cancer cells, supporting both epigenetic regulation and metabolic reprogramming." (PMID 39684755, 2024). "Reversely, UHRF1 regulates gene expression of SET-domain family genes, ultimately promoting the proliferation and metastasis of cancer cells." (PMID 38725075, 2024). "Considering that UHRF1 is an epigenetic modifier aberrantly overexpressed in many cancers, we intended to focus on the relationships between SIRT6 and UHRF1." (PMID 39709438, 2024). "Collectively, these studies show that DNMT1-dependent DNA methylation inheritance is a ubiquitin-regulated process that is partially reliant on UHRF1 and suggest a disrupted UHRF1-DNMT1 ubiquitin signaling axis contributes to PMD formation in cancers." (PMID 39607687, 2024). "UHRF1, an epigenetic regulator known for silencing tumor suppressor genes, negatively impacts SIRT4 levels, thereby facilitating cancer cell proliferation and metabolic reprogramming." (PMID 39682281, 2024). "UHRF1 and DNMT1, which are central regulators of DNA maintenance methylation, are often reported to be highly expressed in cancer cells." (PMID 38297314, 2024). "Among them, only six genes—MMP11, ANGPTL1, GSTM5, IQGAP3, UHRF1, and CCBE1—were shared across all analyzed carcinomas." (PMID 39596491, 2024). "UHRF1 and UHRF2 proteins share a highly similar structural homology with each other, but the expressions of these proteins are different in cancers." (PMID 37628583, 2023).
cancer (continued). "The epigenetic regulator UHRF1 (ubiquitin-like, containing PHD and RING finger domains 1) is a multidomain protein with oncogenic abilities overexpressed in most cancers." (PMID 37630248, 2023). "Thus, in the future targeted chemical inhibition of UHRF1 in cancer may be possible." (PMID 37407562, 2023). "UHRF1, a DDR key-regulator correlated with cancer progression and metastasis, was found in our study significantly decreased in cHL." (PMID 37568720, 2023). "LDHB, PTPRS, UHRF1, and TUBB3 were proposed as universal prognostic and malignancy markers across many cancer types." (PMID 36900348, 2023). "Since both DNMT1 and HDAC1 are well-documented partners of the epigenetic reader UHRF1 in cancer cells, we studied the 24 h effect of BSO on the mRNA expression of the trimeric complex UHRF1, DNMT1 and HDAC1 in cancer cells." (PMID 35566130, 2022). "The poorly differentiated cancer, ATC, overexpresses UHRF1 and has a highly distant metastatic capability, while PTC, a type of well-differentiated cancer, develops slowly and has a good prognosis." (PMID 35996525, 2022). "This study was designed to compare the effects of locally sourced BSO with those of pure TQ on the expression of the epigenetic complex UHRF1/DNMT1/HDAC1 and the related events in several cancer cells." (PMID 35566130, 2022). "We also found that TQ induces auto-ubiquitination of UHRF1 and subsequent degradation in cancer cells by targeting its RING domain, which is the only domain of the UHRF1 structure that exhibits enzymatic activity." (PMID 33922029, 2021). "Thymoquinone also downregulates the expressions of containing plant homeodomain (PHD) and really interesting new gene (RING) finger domains 1 DNMT1,3A,3B, (UHRF1), HDAC1,4,9, G9A, KMT2A,B,C,D,E, and KDM1B genes in Jurkat cells and MDA‐MB‐468 cancer cell lines." (PMID 33747489, 2021). "UHRF1 (Ubiquitin-like containing PHD and Ring Finger 1) is an oncogenic factor over-expressed in different cancer cells and is known by its potent effect in silencing tumor suppressor genes in cancer cells." (PMID 34835969, 2021). "Our results this far showed that UHRF1 and DNMT1 are co-regulated at the level of transcription in various cancer cell lines via the MEK/ERK pathway." (PMID 30696879, 2019). "Further studies with our TR-FRET assay on large chemical compound libraries may yield novel UHRF1 inhibitors, representing a novel class of DNA demethylating agents for development as pharmacological probes of epigenetic mechanisms and as drugs for cancer therapy." (PMID 31105884, 2019). "Using this program we analyzed the expression correlation between UHRF1 and DNMT1 in different cancer cell lines (brain, pituitary, and prostate) and normal tissues (bone marrow) in Homo sapiens." (PMID 30696879, 2019). "In contrast to mESCs, 2i-induced downregulation of UHRF1 and DNMT1 in cancer cells cannot be rescued by proteasome inhibitor and occurs primarily at the level of transcription." (PMID 30696879, 2019). "In this study, we have compared the effect of 2i on UHRF1 and DNMT1 expression in mESCs and human cancer cells." (PMID 30696879, 2019). "As distinct mechanisms were observed for regulation of UHRF1 and DNMT1 by 2i in mESCs and HCT116 cells, we wondered if and how 2i regulates UHRF1 and DNMT1 in various cancer cells." (PMID 30696879, 2019). "We searched for the co-expressed genes for UHRF1 using this program and found that DNMT1 showed a high co-expression score with UHRF1 in cancer samples and normal tissues." (PMID 30696879, 2019). "Together our study reveals distinct regulation of UHRF1/DNMT1 in mESCs and cancer cells and identifies activated MEK/ERK pathway as a driving force for coordinated and aberrant over-expression of UHRF1 and DNMT1 in cancers." (PMID 30696879, 2019).
cancer (continued). "Interestingly, we found that UHRF1 was strongly correlated with immune function, especially T cells-related biological processes, indicating that RP11-424C20.2/UHRF1 axis may control the cancer progression through affecting the interactions between immune and malignant cells." (PMID 31442209, 2019). "To further investigate the potential roles of RP11-424C20.2 in the progression of human cancer, we first blasted its sequence in the human genome and found that there was a 99% similarity between RP11-424C20.2 and its parental gene UHRF1 (NM_001048201.2)." (PMID 31442209, 2019). "To test the role of MEK/ERK pathway in transcriptional activation of UHRF1 and DNMT1 further, we also treated 12 different cancer cell lines with PD0325901 for 48 hours." (PMID 30696879, 2019). "Having established that 2i broadly inhibits UHRF1 and DNMT1 expression in cancer cells, we next explored if GSK3β and/or MEK/ERK pathway were required for UHRF1/DNMT1 expression in cancer cells." (PMID 30696879, 2019). "However, it was unexpected that hypermethylated genes would continue to be repressed after UHRF1 depletion, as it is well documented that UHRF1 acts as a hub to recruit multiple proteins, including DNMT1, HDAC1, G9a, and EZH2, to repress cancer-associated genes in cancer cells." (PMID 31064417, 2019). "We next attempted to determine if the MEK/ERK pathway is broadly required for elevated expression of UHRF1 and DNMT1 in cancer." (PMID 30696879, 2019). "A significant decrease was also found in the expression levels of crucial epigenetic players UHRF1, DNMT1, and HDAC7, known to inhibit the expression of several tumor suppressor genes in cancer (LogFC<−1.7; p < 0.001)." (PMID 31482051, 2019). "To test if these transcription factors also control UHRF1 and DNMT1 expression in other cancer cells, we carried out the same experiments in A549 cells." (PMID 30696879, 2019). "Together these data provide evidence that 2i broadly regulates UHRF1 and DNMT1 expression in various cancer cells, and does so primarily at the level of transcription." (PMID 30696879, 2019). "Taken together, these data indicated that UHRF1 and DNMT1 are co-expressed in different tissues and cancers." (PMID 30696879, 2019). "Antibody-based blocking of CD47 led to down-regulation of UHRF1 expression, concurrent with a re-expression of p16(INK4A), leading to decreased cell proliferation in both cancer cell lines." (PMID 29899856, 2018). "Through these properties, the tandem UHRF1/DNMT1 plays a role during cell proliferation and therefore in development and cancer." (PMID 28881702, 2017). "Each guide strand and passenger strand coordinately regulates oncogenic genes as observed in several cancers, e.g., pre-miR-145: MTDH and UHRF1; pre-miR-139: MMP11; pre-miR-150: SPOCK1." (PMID 28902136, 2017). "UHRF1 levels have been well correlated with Ki67 and PCNA which are widely used proliferation markers in cancers." (PMID 28881702, 2017). "In this study, we found that UHRF1, the master regulator of epigenetic modifications, was directly suppressed by miR-101 in RCC cells and that its expression enhanced cancer cell migration and invasion." (PMID 27487138, 2016). "For further exploration, we selected five genes that have been previously experimentally demonstrated in other cancer setting in humans, CXCL8/IL8, UHRF1, BRCA1, MCM10, and CDKN3." (PMID 26859141, 2016). "The epigenetic reader UHRF1 (Ubiquitin-like, containing PHD and RING Finger domains 1), an oncogene overexpressed in various human cancer cells is one of the major players involved in apoptosis inhibition by inducing epigenetic silencing of TSGs." (PMID 27839516, 2016). "Having established that both UHRF1 and UHRF2 target DNMT3A for degradation and that downregulation of DNMT3A correlates with DNA hypomethylation, we next investigated the expression profiles of UHRF1 and UHRF2 in various cancers." (PMID 27462454, 2016).
cancer (continued). "EGFP expression was decreased in the cancer cells that were cotransfected with EGFP-MBD1 and UHRF1 plasmid compared with cells transfected with EGFP-MBD1 alone." (PMID 27507047, 2016). "As an interesting perspective in the field of cancer therapy, we have recently identified an inhibitor of UHRF1 (a uracil derivative) that targets the SRA domain with subsequent impact on DNMT1/UHRF1 interactions and decrease in global DNA methylation." (PMID 27839516, 2016). "We present evidence that UHRF1/2 overexpression is likely a common mechanism for suppressing DNMT3A activity and consequently widespread DNA hypomethylation in cancers." (PMID 27462454, 2016). "Significantly, by analyzing the unrestricted paired tumor and normal control RNA-seq data available in the TCGA database, UHRF1 and to a less extent UHRF2 are found to be substantially overexpressed in all types of cancers." (PMID 27462454, 2016). "A causal network modeling meta-analysis further filtered this list down to only three genes, predicting UHRF1 and WHSC1 to be oncogenic master regulators of the cancer DNA methylome, and CBX7 to be a key tumor suppressor." (PMID 26169266, 2015). "For example, UHRF1 and RGS3 are both overexpressed in general in cancers but they showed evidence of increased expression in late stage disease (significantly enhanced in patients with distant and local metastases respectively)." (PMID 25889361, 2015). "Ubiquitin-like with PHD and RING finger domains 1 (UHRF1), as an epigenetic regulator, plays important roles in the tumorigenesis and cancer progression." (PMID 25272010, 2014). "UHRF1 was demonstrated to target PML for degradation by mediating its polyubiquitination in human umbilical vein endothelial cells (HUVEC) and cancer cell lines." (PMID 23730625, 2013). "UHRF1 (Ubiquitin-like, containing PHD and RING Finger domains, 1), over-expressed in various cancers, is an essential protein required for the maintenance of DNA methylation patterns." (PMID 22412883, 2012). "The human UHRF1 protein (ubiquitin-like containing PHD and RING finger domains 1) has emerged as a potential cancer target due to its implication in cell cycle regulation, maintenance of DNA methylation after replication and heterochromatin formation." (PMID 22096602, 2011). "Over-expressed in numerous cancers, Ubiquitin-like containing PHD Ring Finger 1 (UHRF1, also known as ICBP90 or Np95) is characterized by a SRA domain (Set and Ring Associated) which is found only in the UHRF family." (PMID 21496237, 2011). "Doxorubicin, a widely used chemotherapeutic agent known to regulate DNA damage, cell-cycle arrest, and apoptosis, can perturb the expression of several cancer driver genes (GADD45B, UHRF1, CDC6, etc.)that are involved in cell-cycle regulation, from this high-throughput data analysis." (PMID 41431699, 2025). "One of these, UHRF1/2, recruits DNMT1 to hemimethylated DNA, and its overexpression plays a role in the silencing of tumor suppressor genes, as well as in migration, proliferation, and metastasis in various cancers." (PMID 40558829, 2025). "Quite a few E3s have been identified to mediate the proteasomal degradation of PML, including KLHL20, UHRF1, UBE3A and RNF4, which may drive the development of cancers at least partially through PML downregulation." (PMID 40002221, 2025). "As for any other drug, a prerequisite for UHRF1 inhibitors to be useful is the possibility to treat cancer cells without harming healthy cells." (PMID 40595593, 2025). "For instance, UHRF1 and RNF112 had higher methylation across some cancer types than normal cells." (PMID 40591126, 2025). "In essence, the intricate interplay between UHRF1 and HDAC1 highlights the significance of these interactions in gene regulation, particularly in the context of epigenetic control and cancer, and underscores the therapeutic potential of targeting this duo in certain disease scenarios." (PMID 39051184, 2024).